BRCA1 (BRCA1 DNA repair associated)
Diseases named in the same sentence as BRCA1 in open-access papers (continued):
Sharing a sentence is not in itself a finding about the gene and the disease.
ovarian carcinoma (continued). "The ovarian cancer risk for BRCA1 mutation carriers is estimated to be 26% by age 70 years." (PMID 11857015, 2002). "To date, two breast and ovarian cancer predisposing genes have been identified – BRCA1, and BRCA2." (PMID 11857010, 2002). "Carriers of BRCA1 mutation may have higher risk of both breast and ovarian cancers." (PMID 41488281, 2026). "First, there is a need for more comprehensive studies on the molecular and genetic drivers of metastasis, particularly in the context of ovarian cancer mutations, such as BRCA1/2 and homologous recombination deficiencies, which may predispose tumors to specific metastatic patterns." (PMID 40109727, 2025). "Although emerging evidence suggests that the location of mutations may influence clinical outcomes, no discernible pattern has been observed indicating which location of the BRCA1/2 mutation influences clinical outcomes in ovarian cancer patients with BRCA1 and BRCA2 mutations." (PMID 40427158, 2025). "Consequently, TLK deficiency induces PARPi resistance in triple-negative breast cancer (TNBC) and ovarian cancer (OVCA) cell lines with BRCA1 deficiency, as TLK deficiency in BRCA1-depleted cells, impairs 53BP1 recruitment to DSBs and reduces NHEJ efficiency, while restoring HR." (PMID 39844055, 2025). "Although studies have suggested that the location of BRCA1/2 mutations may influence clinical outcomes, no discernible pattern has been observed indicating which mutation location influences clinical outcomes in patients with ovarian cancer with BRCA1/2 mutations." (PMID 40427158, 2025). "Studies have shown that abnormal methylation of BRCA1/2 genes in ovarian cancer tissue is closely associated with microbial-associated inflammation, further demonstrating the ability of vaginal microbiota metabolism to promote ovarian cancer development by epigenetic modifications." (PMID 40732683, 2025). "The presence of a BRCA1 mutation might also influence the decision to consider prophylactic surgeries or interventions in the future, such as oophorectomy (removal of the ovaries) to reduce the risk of ovarian cancer." (PMID 40949480, 2025). "It is possible that BRCA1 loss-of-function mutations not only contribute to cancer susceptibility but also may affect the gut and cervicovaginal microbiota, further complicating the understanding of ovarian cancer development." (PMID 41148804, 2025). "Furthermore, a detailed medical history and clinical examination must be performed at the beginning of each pregnancy to identify any predisposing genetic factors (such as BRCA1/BRCA2 mutation carrier status or a strong family history of breast or ovarian cancer) or other malignancy risk factors." (PMID 39941758, 2025). "The available data allows for the following conclusion: Carriers of BRCA1 mutations diagnosed with BC may experience several advantages from early oophorectomy, such as a lower incidence of second primary ovarian cancers and a reduction in BC-related mortality." (PMID 41303742, 2025). "Similarly, a study published in The Journal of Clinical Oncology in 2020 reported that among patients with BRCA1/2-mutated ovarian cancer who received niraparib, another FDA-approved PARPi, the objective response rate was 73%, and the median progression-free survival was 12.9 months." (PMID 39844055, 2025). "Interestingly, the patient carrying the germline variant BRCA1 c.1387A>T (p.Lys463*), at the BRCA1 Ovarian Cancer Cluster Region, classified as likely pathogenic (accordingly to ACMG) and presenting LOH in the tumoral tissue, did not present familial or personal cancer history consistent with HBOC." (PMID 38308422, 2024). "Furthermore, this investigation tackled the obstacles associated with assessing functionality and determining the pathogenicity of new BRCA1 variants, which are known to substantially elevate the risk of breast and ovarian cancers and are typically identified through clinical genetic testing." (PMID 38195537, 2024).
ovarian carcinoma (continued). "Notably, while HRDlow sarcoma cells formed RAD51 nuclear foci upon olaparib- and trabectedin-induced DNA damage, neither formation of RAD51 nuclear foci nor increased RAD51 nuclear intensity were observed in HRDhigh sarcoma cells and BRCA1-mutated ovarian cancer cells." (PMID 39535612, 2024). "We hypothesised that because epithelial ovarian cancers containing a germline BRCA1/2 mutation often have a better radiological response to platinum-containing chemotherapy compared to tumours with germline BRCA1/2 wild type, they would also have a better histopathological response to NACT." (PMID 39550490, 2024). "The first molecular investigation into the role of BRCA genes in breast and ovarian cancer within Romania was carried out in 2010, when 17 patients from unrelated hereditary breast and ovarian cancer families in northeastern Romania were screened for BRCA1 and BRCA2 mutations." (PMID 39272683, 2024). "However, poly(adenosine diphosphate ribose) polymerase (PARP) inhibitors have changed the game altogether for individuals with advanced ovarian cancer, especially those carrying breast cancer (BRCA1/2) mutations or so-called homologous recombination deficiencies (HRDs)." (PMID 39360040, 2024). "Therefore, treatment with oral poly-adenosine diphosphate-ribose polymerase (PARP) inhibitors such as olaparib, which is an effective drug for patients with platinum-sensitive HBOC or HRD-positive ovarian cancer, can be used in patients with GC harboring BRCA1/2 mutations with PVs and/or HRD." (PMID 39590127, 2024). "Thus, L-leucine restriction in the diet may help treat ovarian cancer with BRCA1 mutation by less activating mTOR pathway." (PMID 38468344, 2024). "The incapability of ctDNA to seek somatic BRCA1/2 mutations might result from the spatial and temporal heterogeneity of somatic BRCA1/2 mutations in a patient’s tumour and the rare chances of ovarian cancer to disseminate through the vasculature in contrast to most other types of carcinomas." (PMID 38755585, 2024). "A meta-analysis of ovarian cancer cohorts across 22 Arab-predominant countries, has revealed eight ovarian-cancer linked mutations apparently unique to Arab populations, six of which were only observed in Saudi Arabia, with the most commonly observed mutations being in BRCA1 (77% of patients)." (PMID 37306523, 2023). "In the case of disease recurrence of platinum-sensitive high-grade epithelial ovarian cancer, the PARPi olaparib, niraparib, and rucaparib are approved as maintenance therapy after response to second-line platinum-based chemotherapy, independently of the BRCA1/2 mutational status." (PMID 37568590, 2023). "We show for the 1st time the feasibility and clinical usefulness of performing HRD testing encompassing both BRCA1/2 pathogenic variant analysis as well as genomic instability testing on cftDNA from peritoneal fluid obtained from patients with newly diagnosed advanced ovarian cancer." (PMID 37932736, 2023). "For those who have not elected RRSO, which is the recommended risk management option for ovarian cancer in carriers of a pathogenic, likely pathogenic (P/LP) BRCA1/2 variant, TVUS and serum CA-125 may be considered at the clinician’s discretion starting at 30 to 35 years of age." (PMID 36837501, 2023). "Additionally, our study demonstrated that relatives of BRCA1 carriers have a significantly higher risk for ovarian cancer (RR = 4.72) than relatives of BRCA2 carriers, suggesting that relatives of BRCA1 carriers should be more aware of ovarian cancer than BRCA2 carriers." (PMID 36861435, 2023). "Thus, the objective of this study was to develop and apply a decision-analytic model for the evaluation of the long-term effectiveness and cost-effectiveness of different strategies to prevent breast and ovarian cancer in women with BRCA-1/2 mutations in Germany." (PMID 37365514, 2023).
ovarian carcinoma (continued). "In a study published in 2022 conducted on 490 Romanian patients diagnosed with BC and ovarian cancer (OC), this variant was reported as the most frequent variant associated with OC and the second most frequently associated with BC, accounting for 30 % of BRCA1 mutations in the Romanian population." (PMID 36980780, 2023). "Similarly, ovarian cancer can be caused by pathogenic variants in BRCA1/2 and the MMR genes (LS)." (PMID 36647026, 2023). "Finally, we derived a single model of biallelic BRCA1 loss in ovarian cancer." (PMID 36883553, 2023). "Moreover, the WEE1 inhibitor adavosertib alone or in combination with olaparib was assessed in a Phase II study enrolling patients with recurrent ovarian cancer with previous progression on PARPi treatment, approximately half with a germline or somatic BRCA1/2 mutation." (PMID 37430137, 2023). "These new results more than double the number of variants in the BRCA1 amino terminus for which we have functional results in DNA repair and are consistent with the results of other functional assays and with variants with known impacts in clinical predisposition to breast and ovarian cancer." (PMID 37578980, 2023). "A preclinical study on PDX models with BRCA1-methylated ovarian cancer further showed that methylation status of all BRCA1 copies is associated with sensitivity of rucaparib, suggesting that complete methylation of BRCA1 promoter might be utilized to predict the PARPi response in the clinic." (PMID 36284291, 2022). "A urine test also lends itself to home-based self-sampling with postal return to the laboratory for asymptomatic women at increased risk of ovarian cancer (eg BRCA1/2 pathogenic variant carriers), for whom repeat sampling at regular intervals could be important for early detection." (PMID 35166350, 2022). "Therefore, future studies with samples from more patients with germline BRCA1 mutations may help to determine the cause-and-effect relationships between germline BRCA1 mutations and ovarian cancer development." (PMID 36076202, 2022). "Comparing a BRCA1-deficient mouse ovarian cancer cell line to one with derived PARPi resistance, it was revealed that the resistant cell line displays suppressed ssDNA gap formation, suggesting that decreased gap accumulation could explain the resistance observed." (PMID 36568963, 2022). "Furthermore, the PARP inhibitors' extraordinary activity in cellular systems lacking HR repair has been demonstrated in preclinical investigations by a synthetic lethality rationale, and this activity has been confirmed in clinical trials in BRCA1/2 mutation carriers with ovarian carcinomas." (PMID 35964058, 2022). "However, in breast and ovarian cancer cells, BRCA1 is mutated." (PMID 35740092, 2022). "We are currently conducting biochemical studies and analysing additional ovarian cancer samples, as well as patient-derived xenografts, enriched for BRCA1/2 mutants, to understand whether the BRCA1/2 mutational status is associated with or determines the CCDC6 increased turnover." (PMID 35964058, 2022). "Analysis of clinical ovarian cancer samples showed that exon 11 mutation carriers had worse overall survival when compared with non-exon 11 mutation carriers, probably due to less sensitivity to platinum-based chemotherapy by the cells with residual BRCA1 function of the hypomorphic protein." (PMID 35681784, 2022). "However, because the findings of this evaluation reflected the general clinical conditions of managing patients with PSR ovarian cancer and BRCA1/2 mutation, this study might be a valuable reference for decision makers." (PMID 36034834, 2022). "For example, one of the studies with greater mutation frequencies for BRCA1/2 (33.3%) included not only index patients but also their relatives, increasing the chances of detecting variants if we take into account that all these patients belonged to families with several breast/ovarian cancers." (PMID 35451682, 2022).
ovarian carcinoma (continued). "However, our results support the use of olaparib as maintenance therapy for PSR ovarian cancer patients with a BRCA1/2 mutation as olaparib is not only highly effective but also has strong potential to become a cost-effective treatment option when the cost is reduced by 60% in China." (PMID 36034834, 2022). "This may be because BRCA1/2 mutation is a driving factor of ovarian cancer." (PMID 38089758, 2022). "Moreover, RBBP8 deficiency has been associated with increase the susceptibility of breast and ovarian cancer to poly ADP ribose polymerase (PARP) inhibitors in a manner similar to BRCA1 mutations which suggests a possible benefit of difficult to manage MIBC from this approach." (PMID 36076047, 2022). "However, in patients who are at high risk of ovarian cancer, such as patients with BRCA1/2 mutations, there may be some utility and benefit." (PMID 33477343, 2021). "However, mutations in BRCA1 per se only explain a part of familial breast and ovarian cancers." (PMID 33623049, 2021). "For instance, it is unknown to what extent findings would generalize to contexts where individuals can learn about genetic risk for severe diseases, such as genetic testing for high-penetrance familial risk such as BRCA1/2 genetic testing for hereditary breast and ovarian cancer." (PMID 33987754, 2021). "Furthermore, results from the PRIMA/ENGOT-OV26/GOG-3012 trial demonstrated niraparib efficacy for BRCA1/2 wildtype patients and patients with intact homologous recombination repair in addition to efficacy for BRCA1/2 mutated and homologous recombination repair-deficient ovarian cancer patients." (PMID 33419231, 2021). "In addition, the frequency of germline BRCA1/2 gene mutation carriers and the ratio of germline BRCA1 to BRCA2 mutations in ovarian cancer patients may vary depending on the population." (PMID 34356066, 2021). "Approximately 5% of breast and 15% of ovarian cancer cases were previously thought to arise due to mutations in BRCA1/2; however, HRDetect, a recently proposed weighted model which predicts BRCA1/2 deficiency, has estimated that up to 22% of breast tumors may carry mutations in these genes." (PMID 35008272, 2021). "Points are given to cases of breast or ovarian cancer on the same side of a family, with additional points added or subtracted based on tumour pathology; a Manchester score of 15 equates to a 10% likelihood of detecting an underlying BRCA1/2 variant and a score of 20 to a 20% likelihood." (PMID 34866136, 2021). "Additionally, 6 cases were identified with lung/ovarian cancer carrying CH mutations in BRCA1/2 that might be particularly sensitive to PARP inhibitors such as olaparib, rucaparib and talazoparib." (PMID 34658138, 2021). "BC or ovarian cancer caused by BRCA1 Asp1362fs may develop later." (PMID 34570441, 2021). "Global proteomic analysis of BRCA1-deficient ovarian tumor specimens has identified that loss of BRCA1 associates with altered expression of several factors involved in regulating cell mobility and adhesion, and has a strong association with aggressive ovarian cancers." (PMID 35008272, 2021). "While it is difficult to establish cause-and-effect relationships, several studies indicate that some miRNA expression patterns may be associated with: i) increased breast/ovarian cancer risk; ii) some modifiable nutrition/lifestyle risk factors; iii) BRCA1/2 mutations." (PMID 34552867, 2021). "Although COSMIC has identified somatic MUTYH mutations in 0.24% (3/1229) of curated ovarian cancers, many oncology practices only test ovarian cancer patients with next-generation sequencing for somatic BRCA1/2 mutations or mismatch repair deficiency, suggesting this rate may be an underestimate." (PMID 33419231, 2021). "Reduced expression or activity of BRCA1 due to mutations or epigenetic silencing might result in the reactivation of the aromatase gene, which might lead to abnormal estrogen synthesis and thereby promote breast and ovarian cancer development." (PMID 35008272, 2021).
ovarian carcinoma (continued). "In the future, iPSC-derived BRCA1+/− iMSCs could have important applications in high-throughput drug screening and the testing of new drugs to prevent or to cure hereditary breast and/or ovarian cancers by specifically targeting the stromal compartment with germline BRCA1 mutations." (PMID 33513753, 2021). "Notably, 10–15% of all ovarian cancers are associated with BRCA1/2 pathogenic variants." (PMID 33327492, 2020). "Interestingly, approximately a quarter to half of ovarian cancers with germline BRCA1/BRCA2 mutations exhibit the reversion of the inherited mutation and chemoresistance after chemotherapy, suggesting that in vivo retrieval of BRCA function is a potent oncogenic event to resist unwanted DNA damage." (PMID 32269964, 2020). "The identification of founder and novel private mutations on BRCA1/2 as well as functional variants on genes involved in the homologous recombination pathway has significant impact on genetic screening and clinical management of breast and ovarian cancer patients." (PMID 33240314, 2020). "As there is widespread agreement that only about 16% of heritable breast and ovarian cancer risk is attributable to the high-penetrance BRCA1/2 mutations, it seems likely that many BC cases in BRCA1/2-negative families could be attributable to moderate- or low-penetrance genes." (PMID 31968594, 2020). "There seems to be no increased risk of developing breast or ovarian in patients harbouring BRCA1/2 mutations through controlled ovarian stimulation, yet data in the literature is lacking regarding with paucity of studies looking at controlled ovarian stimulation in patients with ovarian cancer." (PMID 32419845, 2020). "Furthermore, understanding the role of BRCA1/2 variants in ovarian cancer has allowed for the development of targeted therapies, namely PARP (poly[adenosine diphosphate–ribose] polymerase) inhibitors, which improve progression-free survival in selected women with ovarian cancer." (PMID 33086730, 2020). "As such, BRCA1 methylation may be the cause of a significant number of ovarian cancers." (PMID 31225507, 2019). "Furthermore, we show in the ovarian cancer cohort how this has prognostic implication, superseding what could be derived from gene-based biomarkers (i.e. if only BRCA1 and BRCA2 mutation status were considered)." (PMID 30794536, 2019). "In our study, we used a 21-gene panel to detect mutations including in BRCA1/2 and other tumor suppressor genes that potentially predispose an individual to breast or ovarian cancer to improve knowledge regarding the relationship of a patient’s gene mutation spectrum to ovarian cancer risk in China." (PMID 31472684, 2019). "In addition, somatic BRCA1/2 mutations are present in 3.0–7.9% of cases in ovarian cancer patients." (PMID 30940100, 2019). "However, only 20% of hereditary ovarian cancers have shown mutations in the locus of BRCA1/2." (PMID 31472684, 2019). "However, alterations in BRCA1/2 genes may also be the result of either somatic mutations, or epigenetic silencing in sporadic ovarian cancers." (PMID 31374917, 2019). "Besides mutation, hypermethylation of the promoter of BRCA1, which is observed in approximately 10–15% of sporadic ovarian carcinomas, and more especially in serous carcinomas, could also predict response to PARP inhibitors." (PMID 29882921, 2018). "Therefore, the overall verdict of this study is that the program for diagnosing a germline mutation in the BRCA1/2 genes and for preventative strategies should be considered cost effective when its impact on family members of patients diagnosed with ovarian cancer is assessed." (PMID 30517521, 2018).